CDC25B (cell division cycle 25B)
Diseases named in the same sentence as CDC25B in open-access papers (continued):
Sharing a sentence is not in itself a finding about the gene and the disease.
tumor (61 papers, 2001 to 2025). "It was suggested that high CDC25B expression was associated with higher tumor differentiation in patients." (PMID 39371450, 2024). "Consistently, IHC results also showed that CDC25B staining was also obviously decreased in tumor xenograft with deficiency of METTL3." (PMID 35287752, 2022). "Looking in more detail at the tumor suppressive function of Cdc25B, we found that increased Cdc25B expression caused inhibition of cell growth in human normal fibroblasts." (PMID 33745968, 2021). "The expression of P‐MAPK14 was significantly associated with the expression of CDC25B at the protein level in tumor samples." (PMID 31856414, 2020). "In this study, we found that high expression of CDC25B also caused an increase in the abundance of lymphocytes and overexpression of immune checkpoints within the tumor cells, which creates a proinflammatory and proimmune microenvironment; it causes an overactivation of the TME." (PMID 39371450, 2024). "The goal of the current study was to determine whether the level of CDC25B in PDX tumor models is associated with sensitivity to BETi or to gemcitabine." (PMID 39534870, 2024). "Although our results suggest that the highest level of CDC25B expression seems be important for GC initiation in our population, previous studies described its increased expression associated with advanced tumor stage, deeper invasion, and metastasis in East Asian population." (PMID 27863420, 2016). "CDC25B was positively correlated with tumor-infiltrating lymphocytes (TILs), Th1 cells, and macrophages, while negatively correlated with T-cell co-stimulation, B cells, and CCR." (PMID 41194984, 2025). "The correlation of CDC25B expression with certain tumor immune checkpoints suggests that CDC25B participates in tumor immune response." (PMID 39371450, 2024). "Our screen showed that 15/20 tumor models expressed low levels of CDC25B, 4/20 models expressed moderate levels, and 1/20 tumor models expressed high levels of CDC25B." (PMID 39534870, 2024). "CDC25B was also involved in the formation of the tumor microenvironment (TME) and immune processes in HCC, and the high expression of CDC25B made patients less sensitive to some drugs." (PMID 39371450, 2024). "The overexpression of CDC25B we observed in gemR tumors is consistent with unregulated cell cycle progression seen with tumor progression." (PMID 39534870, 2024). "The data suggest that CDC25B warrants further investigation as a potential drug target in overcoming gemcitabine resistance in this tumor type." (PMID 39534870, 2024). "We next evaluated the efficacy of the BETi JQ1 or gemcitabine in PA16 CDC25B-low and PA18 CDC25B-high PDX tumor models." (PMID 39534870, 2024). "Repeated exposure of PDAC cells in vitro or tumor models in vivo to gemcitabine increases levels of CDC25B." (PMID 39534870, 2024). "We propose that the CDC25i inhibits the activity of residual CDC25B, resulting in cell cycle stasis and inhibition of tumor progression." (PMID 39534870, 2024). "In the study, we found that CDC25B was highly expressed and correlated with poor prognosis and degree of tumor differentiation in HCC patients in both database and HCC clinical samples." (PMID 39371450, 2024). "In conclusion, our results demonstrated the adverse effects of CDC25B on tumor differentiation and prognosis in HCC patients." (PMID 39371450, 2024). "This study characterizes levels of CDC25B expression in our series of 20 pancreatic PDX tumor models." (PMID 39534870, 2024). "The results showed that tumor tissues at all levels of differentiation exhibited differences in CDC25B expression compared with normal tissues." (PMID 39371450, 2024). "Collectively, these results suggest that METTL3/CDC25B promotes HNSCC tumor growth and angiogenesis." (PMID 35287752, 2022).
tumor (continued). "As confirmed by qPCR and western blot, CDC25B expression was downregulated upon knockdown of METTL3 in tumor tissues." (PMID 35287752, 2022). "FVB/nJ mice immunized with CDC25B or COX2 peptides showed significant inhibition of growth of the syngeneic MC38 tumor compared to control (p<0.0001)." (PMID 34526999, 2021). "As expected, we observed significant MC38 tumor inhibition in mice immunized with the CDC25B (p<0.001) or COX2 (p=0.043) vaccine and treated with a control IgG." (PMID 34526999, 2021). "The mean tumor volume at the termination of the study from mice receiving the CDC25B (365 ± 165 mm3) or COX2 multi-peptide vaccine (211 ± 106 mm3) was significantly reduced as compared to the control (883 ± 481 mm3; p<0.001 for both)." (PMID 34526999, 2021). "The finding of senescence induction by increased CDC25B expression provides an explanation to the tumor-suppressive role of Cdc25B." (PMID 33745968, 2021). "In the prophylactic setting, after immunization with CDC25B or COX2 peptides mice treated with AOM developed significantly fewer tumors as compared to controls (p<0.0002) with 50% of mice remaining tumor free in each antigen group." (PMID 34526999, 2021). "The CDC25B regulates cell cycle progression in various cancer cell lines and has contributed to tumor growth." (PMID 35003004, 2021). "Recent studies have shown that high expression levels of CDC25B can promote the malignant transformation of cells and promote tumor growth." (PMID 31856414, 2020). "To broaden our research in novel anti-tumor lead compounds, we selected Cell Division Cycle 25B (CDC25B), a specific tyrosine phosphatase, and epidermal growth factor receptor (EGFR), an Erb family receptor, as screening targets." (PMID 31480659, 2019). "The anti-tumor activity of WG-391D involved down-regulation of CDC25B and subsequent inactivation of CDC2 and AKT." (PMID 31024841, 2019). "In an effort to discover new bioactive anti-tumor lead compounds, a specific tyrosine phosphatase CDC25B and an Erb family receptor EGFR were selected as drug screening targets." (PMID 31480659, 2019). "Mir-152 is a tumour suppressor, which inhibits tumour cell growth both in vitro and in vivo by repressing Cell Division Cycle 25B (CDC25B), an important cell cycle regulator." (PMID 30037059, 2018). "In conclusion, decreasing YWHAE and increasing CDC25B expression seems to be important for tumor development, especially in diffuse-type tumors of early-onset." (PMID 27863420, 2016). "Decreased prostate carcinogenesis in SPDEF-deficient mice was associated with decreased proliferation of tumor cells and reduced expression of Cdc25b, Cyclin B1, Plk-1, AuroraB, and Topo2alpha, factors that are critical for tumor cell proliferation." (PMID 25254494, 2014). "Our findings indicate that the levels of CDC25B-Abs in sera from patients with ESCC are significantly higher than those of other tumor markers." (PMID 20813067, 2010). "The concentration of CDC25B autoantibodies in serum was significantly correlated with tumor stage (P < 0.001)." (PMID 20813067, 2010). "The rate of CDC25B-Abs seropositivity in patients with ESCC was significantly higher than the seropositivity rates of tumor markers SCC-Ag, CEA and CYFRA21-1." (PMID 20813067, 2010). "We then analyzed the potential prognostic value of CDC25B-Abs in different subgroups of patients stratified according to the clinical stage of the patient's tumor, T classification and N classification." (PMID 20813067, 2010). "Detection of serum CDC25B-Abs is superior to detection of the tumor markers CEA, SCC-Ag and CYFRA21-1 for diagnosis of ESCC, and CDC25B-Abs are a potential prognostic serological marker for advanced ESCC." (PMID 20813067, 2010).
tumor (continued). "The extract of Eca-109 cells, which presented the highest CDC25B protein level among the ESCC tumor cell lines tested (Eca-109, Kyse140, TE-1 and the immortalized cell line NE-3), was used as the source of CDC25B antigen for reverse capture ELISAs." (PMID 20813067, 2010). "The clinicopathologic significance of CDC25B serum autoantibodies was compared to that of the tumor markers carcinoembryonic antigen (CEA), squamous cell carcinoma antigen (SCC-Ag) and cytokeratin 19 fragment antigen 21-1(CYFRA21-1)." (PMID 20813067, 2010). "Overall, our results demonstrate that a moderate and unscheduled increase in CDC25B level, as observed in a number of human tumours, is sufficient to overcome the S-phase checkpoint efficiency thus leading to replicative stress and genomic instability." (PMID 20128929, 2010). "Quantitative real-time polymerase chain reaction and immunohistochemical staining of patient samples confirmed the significant over-expression of CDC25B in HCC compared to non-tumor liver samples (P < 0.001)." (PMID 18269767, 2008). "Our group previously studied the gene expression profiles in over 200 liver tissue samples, and identified CDC25B as one of most significantly over-expressed genes in HCC compared to non-tumor liver." (PMID 18269767, 2008). "Immunohistochemistry of liver tissue arrays further confirmed the over-expression of CDC25B protein in HCC tissues compared to non-tumor liver tissues (P < 0.001)." (PMID 18269767, 2008). "The expression of cdc25A and cdc25B has been studied in some human neoplasms and various results have been obtained." (PMID 12085185, 2002). "Additionally, CDC25B can enhance the activation of estrogen receptor, androgen receptor (AR), and progesterone receptor, thereby promoting tumor malignancy." (PMID 40216745, 2025). "Efforts to develop anti-tumor agents that target CDC25B have been only marginally successful." (PMID 39534870, 2024). "Because the literature documents an association between overexpression of CDC25B and drug and radiation resistance, we next assessed whether gemcitabine-resistant (gemR) PDX models of PDAC had higher levels of CDC25B than the parent tumor counterparts." (PMID 39534870, 2024). "CDC25B was first designated as an oncogene when it was found to induce oncogenic transformation of mouse embryonic fibroblasts in vitro in cooperation with activated mutant H-Ras and to induce tumor formation in nude mice." (PMID 39534870, 2024). "Finally, we investigated the mutation of CDC25B in HCC and the relationship between CDC25B expression and tumor cell infiltration of lymphocytes and some immune checkpoints as well as drug sensitivity." (PMID 39371450, 2024). "It suggests that CDC25B may be involved in the regulation of tumor immune response by affecting immune checkpoint activity." (PMID 39371450, 2024). "CDC25B has oncogenic properties that enhance tumor growth and survival." (PMID 37156819, 2023). "This implies that METL3 and CDC25B are expressed in cells with high mitotic activity, whether it is tumor cells or normal cells." (PMID 35637959, 2022). "We previously reported that the BET bromodomain inhibitor JQ1, as a single agent, suppressed PDAC tumor growth in preclinical models and that tumor growth inhibition was concomitant with decreased expression of the G2 cell cycle regulator CDC25B, and increased levels of the DNA damage marker γH2AX." (PMID 34298684, 2021). "These analyses disclosed that the tumor-promoting effects of CDC25B in ESCC development." (PMID 33442418, 2021).
tumor (continued). "We evaluated whether vaccination with epitopes from either CDC25B or COX2 could inhibit lesions in a spontaneous tumor model." (PMID 34526999, 2021). "The mechanism of how increased Cdc25B rendered its tumor-suppressive effect was analyzed." (PMID 33745968, 2021). "Thus, our results provide evidence to support a role of Cdc25B in senescence induction that is related to tumor suppressing." (PMID 33745968, 2021). "P‐MAPK14 could promote tumor proliferation and migration through binding to and affecting the stability of CDC25B." (PMID 31856414, 2020). "After 4 weeks, it was found that the tumor size and weight in MAPK14 knockdown group were significantly lower than those of vector group, while in CDC25B overexpression group, the tumor size and weight were significantly higher than those of the vector group (P < .05)." (PMID 31856414, 2020). "Based on our previous findings, we hypothesized that MYC or CDC25B up-regulation may induce YWHAE down-regulation in GC or YWHAE down-regulation would induce CDC25B up-regulation in this neoplasia, which would also contribute to MYC overexpression." (PMID 27863420, 2016). "Thus, overexpression of Cdc25B is believed to contribute to tumorigenesis by enhancing tumor malignancy." (PMID 22132193, 2011). "Moreover, the combination of CDC25B-Abs and conventional tumor markers, CEA, SCC-Ag, and CYFRA21-1 significantly increased the sensitivity of detection of ESCC." (PMID 20813067, 2010). "In this study, we show that a moderate and unscheduled increase in CDC25B protein level, comparable to the increased level that has been reported to be observed in human tumours, has a critical incidence during S phase through the generation of replication defects." (PMID 20128929, 2010). "We previously reported that aberrant expression of CDC25B in ESCC tumor cells can induce CDC25B autoantibodies in sera of ESCC patients, and antibodies against CDC25B were detected in sera of 36.3% of patients with ESCC, but not in sera of healthy controls, by reverse capture ELISA." (PMID 20813067, 2010). "In order to confirm this observation in a cellular context in which the unscheduled expression of CDC25B is limited to a level frequently observed in many tumour cell lines, we made use of HCT116 cells that were engineered to stably express a moderate level of Ha-CDC25B." (PMID 20128929, 2010). "CDC25B autoantibodies were measured in sera from both 134 patients with primary ESCC and 134 healthy controls using a reverse capture enzyme-linked immunosorbent assay (ELISA) in which anti-CDC25B antibodies bound CDC25B antigen purified from Eca-109 ESCC tumor cells." (PMID 20813067, 2010). "We next studied the in vivo effects of CDC25B suppression on tumor growth." (PMID 18269767, 2008). "Our data provide evidence that the inhibition of CDC25B expression and activity lead to suppression of tumor cell growth and motility, and may therefore be a feasible approach in the clinical management of HCC." (PMID 18269767, 2008).
tumor (continued). "Thus, application of normal fibroblasts could provide additional assessment for the contribution of CDC25B during tumor development." (PMID 33745968, 2021). "Thus, elevation of Cdc25B in early tumor development is likely to be tumor suppressive." (PMID 33745968, 2021). "The scenario might explain the dual function of Cdc25B during tumor development." (PMID 33745968, 2021). "Thus, although PP2A is considered to be a tumor suppressor, it may stimulate tumor progression through additional mechanisms such as, in this case, binding to CDC25B." (PMID 33385163, 2020). "Thus miR-1972 can also perform as a tumour suppressor since it inhibits CDC25B expression." (PMID 27586591, 2016). "CDC25B was overexpressed in HCC tissues and correlated with poor prognosis and the degree of tumor differentiation in patients with HCC." (PMID 39371450, 2024). "In this study, CDC25B was highly expressed in a variety of tumors, including HCC, and correlated with the degree of tumor differentiation in HCC patients." (PMID 39371450, 2024). "The data show that the CDC25B-high PDX tumor model was more sensitive to JQ1 and less sensitive to gemcitabine in vivo than the CDC25B-low model." (PMID 39534870, 2024). "CDC25B expression in HCC cells had a significant correlation with B cells, CD8+ T cells, CD4+ T cells, macrophages, neutrophils, and dendritic cells in tumor cells." (PMID 39371450, 2024). "The remaining six genes (e.g., PPP3CC, ITGA5, ITK, CDC25B, CCND2, and THY1) were expressed at higher levels in CD45+ TAS as compared to CD45+ tumor." (PMID 36230846, 2022). "Immunization with CDC25B and COX2 epitopes consistently suppressed tumor development in each model evaluated." (PMID 34526999, 2021). "In vitro studies using non-colonic cell lines have indicated that miR-148a exerts a tumor suppressive function by targeting several genes such as PXR, TGIF2, MSX1, CDC25B, DNMT1 and DNMT3b." (PMID 23056401, 2012). "In this study, we established a reverse capture ELISA to detect anti-CDC25B antibodies in sera from patients with ESCC and evaluated the clinical values of CDC25B autoantibodies for diagnosis of ESCC and prediction of tumor progression." (PMID 20813067, 2010). "In summary, CDC25B, a key factor involved in cell cycle regulation (mainly G2/M phase), was shown to be overexpressed in HCC tumors and significantly correlated with poor prognosis and degree of tumor differentiation in HCC patients." (PMID 39371450, 2024). "Tumors collected at the end of the experiments showed that M1-21 significantly decreased the size and weight of engrafted tumors compared to controls, correlated with the decreased levels of FOXM1 and FOXM1-regulated CDC25B and PLK1 in M1-21-treated tumor samples." (PMID 37344857, 2023). "Depletion of CD8+ T-cells, however, abrogated the anti-tumor effect of either vaccine and tumor growth was no different from controls (p=0.858 for CDC25B and p=0.087 for COX2)." (PMID 34526999, 2021). "Only the CDC25B and COX2 significantly inhibited tumor growth." (PMID 34526999, 2021). "The levels of CD4+ T-cells infiltrating the tumor were low and no different than levels observed in the control for mice immunized with CDC25B or COX2 peptides (p>0.55 for both)." (PMID 34526999, 2021). "Although one report indicated that protein expression of CDC25B in GBM tissue is not upregulated in cases with chemo- or ratio-resistance, these evidences suggest and an oncogenic rather than a tumor-suppressive role of CDC25B." (PMID 30791455, 2019). "The muscle invasive tumour, however, showed a basal subtype (higher expression of CDH3, CD44, KRT5 and KRT6A) and likewise high aggressiveness (higher expression of KPNA2, BIRC5, CDC25B, COL4A1, and MSN)." (PMID 28916750, 2017).